ENSG00000268361 (novel protein)
Gene: Protein-coding gene on chromosome 19 (43,554,692 to 43,593,036, reverse strand). Ensembl gene ENSG00000268361.
Genetic constraint (gnomAD): Loss-of-function variants: 9 observed, 12.61 expected, observed/expected ratio (o/e) 0.71, 90% interval 0.43 to 1.25. Missense variants: 165 observed, 183.02 expected, observed/expected ratio (o/e) 0.9, 90% interval 0.79 to 1.03. Synonymous variants: 71 observed, 77.24 expected, observed/expected ratio (o/e) 0.92, 90% interval 0.76 to 1.12.